ALDH2 (aldehyde dehydrogenase 2 family member)
Diseases named in the same sentence as ALDH2 in open-access papers (continued):
Sharing a sentence is not in itself a finding about the gene and the disease.
ischemic stroke (continued). "The present study demonstrated that ALDH2 polymorphisms and alcohol consumption were associated with cognitive impairment and dysphagia in patients after ischemic stroke, mainly in patients with the mutant allele." (PMID 34257742, 2021). "The current study was the first case-cohort study describing the effects of ALDH2 polymorphisms and alcohol consumption on cognitive impairment after ischemic stroke." (PMID 34257742, 2021). "Our study provides sufficient evidence for the association between ALDH2 gene polymorphisms and the risk of ischemic stroke." (PMID 29254215, 2017). "Our results provide evidence that variants of ALDH2 gene polymorphisms influence the risk of developing ischemic stroke in Han Chinese population." (PMID 29254215, 2017). "To the best of knowledge, we identified rs886205 and rs7296651 in the ALDH2 gene associated with an increased risk of ischemic stroke." (PMID 29254215, 2017). "This is in contrast with the reports that the ALDH2 dysfunctional A allele was associated with coronary spastic angina and ischemic stroke in Ease Asian populations." (PMID 27927211, 2016). "Together, these findings emphasize that the increased risk of ischemic stroke in individuals with ALDH2 polymorphisms is not only solely attributable to genetic predisposition but also significantly influenced by environmental factors such as alcohol consumption and smoking." (PMID 41324337, 2026). "However, there has been little previous research into the association between ALDH2 genotypes and cognitive impairment after ischemic stroke." (PMID 34257742, 2021). "Therefore, the aim of this study was to evaluate the association of ALDH2 genotypes and alcohol consumption with cognitive function after ischemic stroke." (PMID 34257742, 2021). "In summary, in this study of a Han Chinese sample, we identified two novel ALDH2 tSNPs associated with ischemic stroke susceptibility which indicates that ALDH2 gene may be provide new insights into the etiology of ischemic stroke." (PMID 29254215, 2017). "An association has been reported between brain ALDH2 levels and protection against ischemic stroke." (PMID 27070252, 2016). "However, the influence of ALDH2 polymorphisms and alcohol consumption on cognitive impairment after ischemic stroke remains unknown, as do the possible mechanisms." (PMID 34257742, 2021). "Through statistical analysis, we found that ALDH2 rs886205 [odds ratio (OR) = 6.39; 95% confidence interval (CI) = 1.19-34.38; p = 0.03] and rs7296651 (OR = 9.29; 95% CI = 1.37-63.21; p = 0.02) were associated with increased risk of ischemic stroke in recessive model analysis." (PMID 29254215, 2017). "Thus, it is possible that locus–locus interactions within the ALDH2 gene may be associated with risk for ischemic stroke." (PMID 29254215, 2017). "Baseline characteristics of male patients with first‐ever ischemic stroke, stratified by ALDH2 genotype and alcohol consumption status." (PMID 41324337, 2026). "Clinical characteristics of first‐ever ischemic stroke patients stratified by the ALDH2 genotype (total, male, and female subgroups)." (PMID 41324337, 2026). "Only one woman carrying the ALDH2*1/*2 genotype, who experienced her first‐ever ischemic stroke at the age of 70, reported a history of heavy alcohol consumption." (PMID 41324337, 2026). "Studies have shown that small-molecule activators of aldehyde dehydrogenase 2 (ALDH2) have the potential to become novel therapeutic drugs for ischemic stroke." (PMID 40733191, 2025). "As expected, the lacunar stroke PWAS found that 1 in 4 (ALDH2; 25%) ischemic stroke genes overlapped with 7 lacunar stroke PWAS-significant genes, reflecting their high degree of genetic correlation." (PMID 35733147, 2022). "al. reported a protective effect of ALDH2*2 on atrial flutter, ischemic stroke, cirrhosis and reduced use of calcium channel blockers." (PMID 35749303, 2022).
ischemic stroke (continued). "ALDH2*2 has a lower NAD + coenzyme binding affinity, which reduces the clearance capacity of acetaldehyde, thereby increasing the risk of ischemic stroke." (PMID 36258220, 2022). "Research has proposed that increasing ALDH2 activity can improve ischemic stroke in rats via inactivation of AQP4 expression." (PMID 34362382, 2021). "We further investigated the synergistic effects of ALDH2 genotype and alcohol consumption on the MoCA score and swallowing ability in ischemic stroke patients." (PMID 34257742, 2021). "Emerging evidence supports the notion that increasing ALDH2 activity can improve ischemic stroke in rats by downregulating aquaporin 4 (AQP4) expression." (PMID 34362382, 2021). "For example, a recent clinical study with 18,000 ischemic stroke patients and 70,000 controls identified SNPs in SH2B3 and ALDH2 linked to ischemic stroke, which were also associated with blood pressure." (PMID 31514409, 2019). "Given the important role of ALDH2 in oxidative stress, elucidating the mechanism of its regulation, especially post-transcriptionally, is one key to understanding ischemic stroke." (PMID 29245933, 2017). "Our results echo several previous studies which have shown that ALDH2 is involved in the process of I/R injury or ischemic stroke." (PMID 29245933, 2017). "Previous studies have shown that aldehyde dehydrogenase 2 (ALDH2) plays a role in ischemic stroke progression." (PMID 29254215, 2017). "This study revealed that Taiwanese men carrying the ALDH2*2 allele who reported heavy drinking had a younger age at first‐ever ischemic stroke than their nonheavy counterparts." (PMID 41324337, 2026). "In this study, we aimed to investigate whether alcohol consumption modifies the relationship between ALDH2 genotype and age at first‐ever ischemic stroke." (PMID 41324337, 2026). "A recent meta‐analysis of genome‐wide data across 16 biobanks confirmed a significant association between ALDH2 variants and ischemic stroke in East Asian men (p = 1.67 × 10−24) but not in women (p = 0.126)." (PMID 41324337, 2026). "However, direct evidence for an interaction between ALDH2 genotype and alcohol exposure—particularly its impact on age at first‐ever ischemic stroke—remains limited." (PMID 41324337, 2026). "Interestingly, across all ALDH2 genotypes, women consistently exhibited a later age at ischemic stroke onset compared with men." (PMID 41324337, 2026). "However, the relationship between ALDH2, alcohol consumption, and cognitive function in patients with ischemic stroke is unclear." (PMID 34257742, 2021). "ALDH2 might therefore be a useful biomarker to target for cognitive rehabilitation following ischemic stroke." (PMID 34257742, 2021). "ALDH2 may be involved in the pathogenesis and progression of ischemic stroke in the Han Chinese population." (PMID 34257742, 2021). "The relevance of ALDH2 in providing strong protection toward toxic damage has been described in numerous reports, demonstrating its efficacy in various models of human diseases such as ischemia/reperfusion and ischemic stroke characterized by overwhelming oxidative stress." (PMID 34228649, 2021). "In addition, considering that the lesion site may affect the swallowing function, we further adopted subtypes of ischemic stroke to investigate the interaction of ALDH2 and alcohol consumption on swallowing." (PMID 34257742, 2021). "Targeting ALDH2 may be a useful biomarker for cognitive rehabilitation following ischemic stroke." (PMID 34257742, 2021). "Enhancing ALDH2 activity may become a novel target for patients with ischemic stroke." (PMID 32210721, 2020). "The relevance of ALDH2 in providing strong protection toward toxic insults has been described in numerous reports, demonstrating its efficacy in various models of human diseases such as ischemia-reperfusion and ischemic stroke characterized by overwhelming oxidative stress." (PMID 30538807, 2018).
ischemic stroke (continued). "Furthermore, activation of ALDH2 prevents ischemic stroke by reducing 4-HNE levels." (PMID 27575855, 2016). "As a potential substrate of ALDH2, 4-HNE is commonly considered a specific marker of ischemic stroke injury." (PMID 34257742, 2021). "However, the critical molecular mechanisms of ALDH2 in the mitochondria-related apoptosis of neurons in ischemic stroke has not been clarified yet." (PMID 32210721, 2020).
liver cancer (28 papers, 2014 to 2025). An epithelial or non-epithelial malignant neoplasm that arises from the liver. "For site‐specific cancers, compared to ALDH2‐rs671 GG genotype, AG genotype was associated with a lower oesophageal cancer risk, while AA genotype was associated with a higher liver cancer risk, but the numbers of cases involved were small." (PMID 35048370, 2022). "One of the most common studies is about the regulatory mechanism of ALDH2 gene polymorphism in digestive system cancer, such as esophageal cancer, colorectal cancer, gastric cancer, liver cancer, and pancreatic cancer." (PMID 35269824, 2022). "Recently, it was reported that ALDH2 deficiency promotes alcohol-associated liver cancer by activating oncogenic pathways via oxidized DNA-enriched extracellular vesicles." (PMID 34830779, 2021). "Studies have shown that the ALDH2 Glu504Lys allele increases the risk of liver cancer in alcohol drinkers, but no increased risk is observed in non-drinkers." (PMID 36939783, 2021). "The ALDH2 mutant genotype, ALDH2*2 allele (also known as ALDH2(E487K) or ALDH2 rs671 polymorphism), has been found to be associated with a high incidence of liver cancer in heavy drinkers." (PMID 34071962, 2021). "ALDH2 deficiency promotes liver cancer by activating oncogenic pathways via oxidized DNA-enriched extracellular vesicles." (PMID 31851620, 2019). "Several data lend support to the increased risk of liver cancer in alcoholics carrying genotypes ALDH2*1/*2 and ALDH2*1/*1." (PMID 28805741, 2017). "The ALDH2 rs2238151 appeared inversely associated with liver cancer when comparing T allele carriers to those with the C/C genotype (age and sex-adjusted SBOR: 0.47, 95% posterior limits: 0.24, 0.92)." (PMID 25337902, 2014). "Remarkably, it is indicating that the polymorphisms of ALDH2 might have an important influence on liver cancer." (PMID 36694633, 2023). "The relationship between ALDH2 deficiency and the development of liver cancer was recently proven." (PMID 34071962, 2021). "Interestingly, multiple studies revealed that ALDH2 is highly correlated with the pathogenic mechanism, risk, and survival of liver cancer patients, including HCC." (PMID 32117713, 2020). "Notably, ALDH2 expression has been linked with liver cancer risk, as well as pathogenesis and prognosis, and has emerged as a promising therapeutic target." (PMID 32140062, 2020). "Notably, ALDH2 deficiency has been associated with increased risk of esophageal, head and neck, and liver cancer in alcohol-consuming individuals." (PMID 33147438, 2020). "Indeed, we show that inhibition of ALDH2 increases the occurrence of DPCs and that low expression of ALDH2 is associated with a poor prognosis for liver cancer patients." (PMID 30088263, 2018). "Whether ALDH2*2 can modify the association between alcohol consumption and liver cancer risk requires further investigation." (PMID 28253921, 2017). "Among the six studies that examined the interaction between ALDH2*2 and alcohol drinking on liver cancer risk, three found a synergistic interaction between ALDH2*2 allele and alcohol consumption to increase liver cancer risk, while three found no such interaction." (PMID 28253921, 2017). "Thus, acetaldehyde is generated not only exclusively from the beer aging process, but also from the ethanol metabolism, increasing aero-digestive tract and liver cancer risks in habitual beer drinkers, particularly in individuals carrying ALDH2 gene polymorphisms." (PMID 36430619, 2022). "Thus, on the one hand, the ALDH2 Glu504Lys allele alleviates liver damage in hepatitis B virus-infected individuals; on the other hand, it reduces the risk of liver cancer by reducing alcohol consumption, thus conferring these individuals with a better chance of survival." (PMID 36939783, 2021).
liver cancer (continued). "As both alcohol consumption and hepatitis B virus infection are the risk factors for liver cancer, those carrying the ALDH2 Glu504Lys allele may reduce alcohol consumption among hepatitis B virus-infected individuals, indirectly reducing their risk of developing liver cancer." (PMID 36939783, 2021). "In another study, 6-MSITC at 20 mg/kg and 40 mg/kg reduced ALDH2 enzyme activity and protein expression, alleviating acetaldehyde-induced cytotoxicity in liver cancer cells." (PMID 39125389, 2024). "ALDH2 levels are significantly downregulated in liver cancer tissues than in normal tissues, and low tumor ALDH2 levels are associated with migration-related traits and poor survival." (PMID 37476181, 2023). "Low ALDH2 expression is always responsible for poorer survival and more aggressive behaviors in liver cancer patients." (PMID 36694633, 2023). "For genomic instability, a study has shown that ALDH2 suppression is associated with a higher DNA base excision repair protein (XRCC1, X-Ray Repair Cross Complementing 1) and worse survival in lung and liver cancers." (PMID 37476181, 2023). "As a member of ALDHs family, there are many studies on the relationship between ALDH2 and liver cancer." (PMID 34928471, 2022). "The authors propose a mechanistic link between maternal high-fat diet and the development of liver cancer through the downregulation of two genes, Acyl-CoA synthetase long chain family member 1 (Acsl1) and Aldehyde dehydrogenase family member 2 (Aldh2)." (PMID 35833105, 2022). "ALDH2 is related to the occurrence and development of liver cancer, gastric cancer, and colon cancer." (PMID 33688464, 2021). "In liver cancer patients, we observed a significant impact of ALDH2 mRNA expression on the overall survival rate, whereas the XRCC1 mRNA level itself had no predictive value." (PMID 30088263, 2018). "On the contrary, we found that low ALDH2 mRNA levels, defined by separating values at the median, strongly predict a worse prognosis in lung and liver cancer." (PMID 30088263, 2018). "Surprisingly we observed in this study, by using bioinformatics analyses, that most cancers, especially lung and liver cancers, gamble with lowering their expression of ALDH2 along with overexpressing XRCC1." (PMID 30088263, 2018). "Surprisingly, we found that low ALDH2 expression levels associated with high XRCC1 expression levels are indicative for a poor overall survival, particularly in lung and liver cancer patients." (PMID 30088263, 2018). "A similar role was attributed to ALDH2 for lung and liver cancer patients." (PMID 35512017, 2022). "In addition, ALDH2 promotes the expression of cancer stem biomarkers (e.g., Nanog, Oct4, and Sox2), leading to the proliferation, migration, and invasion of liver cancer stem cells (LCSCs)." (PMID 35477569, 2022). "Overall, studies to date have consistently shown that ALDH2*2 does not independently contribute to liver cancer risk." (PMID 28253921, 2017). "The expression of ALDH2 is decreased by silencing transcription factor FOXM1, which subsequently increases the level of Bax and cleaved-caspase-3 to promote the apoptosis of liver cancer stem cells (LCSCs) as well as inhibit tumorigenesis of LCSCs." (PMID 35269824, 2022). "Surprisingly, despite the existence of different ALDH isoforms, we found that only ALDH2 expression has an impact on liver cancer (data not shown)." (PMID 30088263, 2018). "In human liver cancer cell lines HepG2 and PLC/PRF/5 that express little or no cGAS proteins, stably reconstitution of cGAS via lentiviral infection led to marked suppression of ALDH2 activity, as indicated by reduced NAD+ to NADH conversion." (PMID 41042077, 2025).
gastric cancer (27 papers, 2012 to 2025). A primary or metastatic malignant neoplasm involving the stomach. "Several studies investigated the association of ALDH2 (rs671) polymorphisms with gastric cancers, and a meta-analysis of seven case-control studies evaluated its relationship." (PMID 39063094, 2024). "A recent prospective study assessed the association of ADH1B and ALDH2 polymorphisms with synchronous gastric cancers." (PMID 39063094, 2024). "The risk of inactive ALDH2*2 allele carriers for gastric cancers increased in moderate to heavy drinkers (OR, 1.85; 95% CI, 1.52–2.25), whereas the OR in nondrinkers or mild drinkers was 1.19 (95% CI, 1.05–1.36)." (PMID 39063094, 2024). "The meta-analysis revealed that inactive ALDH2*2 allele carriers exhibited an increased risk of gastric cancers (OR, 1.26; 95% CI, 1.04–1.52)." (PMID 39063094, 2024). "In parallel with an increased local exposure to ADH, the risks of oral, pharyngeal, oesophageal, and stomach cancers among alcohol users with an ALDH2 deficiency are many times higher than in individuals with a functioning ALDH2 enzyme." (PMID 37238685, 2023). "Recently, signature 16 was reported to be associated with gastric cancer of alcohol consumers with an ALDH2 defective allele (rs671)." (PMID 33826001, 2021). "The association with ALDH2 risk allele was also confirmed in esophagus, hepatic and stomach cancers from The Cancer Genome Atlas (TCGA)." (PMID 33826001, 2021). "Polymorphisms in the Aldehyde Dehydrogenase 2 Family Member (ALDH2) gene have been demonstrated to increase the risk of gastric cancer in a Korean population of current or ex-alcohol consumers, as compared to never/rare consumers." (PMID 32899442, 2020). "This study examined the relationship between alcohol consumption and the gastric cancer risk with regard to the ALDH2 rs671 polymorphism." (PMID 28036260, 2017). "In this study, we investigated the roles of alcohol consumption, the ALDH2 rs671 polymorphism, and their interaction in the risk of gastric cancer, with comparison of the differences in results between the sexes." (PMID 28036260, 2017). "An earlier study has shown that ALDH2 Glu504Lys (rs671) polymorphism interacts with alcohol drinking in determining stomach cancer risk." (PMID 29166882, 2017). "Previous case-control studies have reported a correlation between the ALDH2 rs671 G>A polymorphism and the development of stomach cancer, However, the results are still discrepant." (PMID 29254255, 2017). "A multivariate analysis showed that H. pylori-induced chronic atrophic gastritis (CAG) and the ALDH2*1/2*2 genotype were independently associated with the risk of developing gastric carcinoma in alcoholic Japanese men." (PMID 28538665, 2017). "All this information provides entirely novel perspectives for the prevention of gastric cancer, especially among particular risk groups: those with ALDH2 deficiency, atrophic gastritis, Helicobacter pylori infection, and regular use of proton pump inhibitors." (PMID 25831092, 2015). "A mutant allele encoding an inactive subunit of aldehyde dehydrogenase-2 (ALDH2; rs671) was carried by Han Chinese as they spread throughout Eastern Asia, i.e. to the countries with the highest incidence of esophageal and gastric cancers." (PMID 25831092, 2015). "ALDH2 deficiency, achlorhydria and alcohol-associated exposure to intragastric acetaldehyde appear to play a key role in the pathogenesis of gastric cancer." (PMID 25831092, 2015). "Atrophic gastritis is a major risk factor for gastric cancer and also increases the risk of esophageal squamous cell carcinoma, especially in ALDH2-deficient subjects." (PMID 25831092, 2015). "Atrophic gastritis is a major risk factor for gastric cancer and also significantly increases the risk of esophageal squamous cell carcinoma, especially in ALDH2-deficient subjects." (PMID 25831092, 2015).